FOSL2 (FOS like 2, AP-1 transcription factor subunit)
Description:
Controls osteoclast survival and size (By similarity). As a dimer with JUN, activates LIF transcription (By similarity). Activates CEBPB transcription in PGE2-activated osteoblasts (By similarity).
Synonyms: FRA2; FLJ23306; ACED
Tractability: PROTAC: UniProt records ubiquitination sites on it; ubiquitination databases record sites on it.
Gene: Protein-coding gene on chromosome 2 (28,392,448 to 28,417,317, forward strand). Ensembl gene ENSG00000075426.
Subcellular location: Nucleus
Subcellular location (Human Protein Atlas): Nucleoplasm
Gene Ontology:
Molecular function: DNA-binding transcription activator activity, RNA polymerase II-specific; DNA-binding transcription factor activity, RNA polymerase II-specific; protein binding; RNA polymerase II transcription regulatory region sequence-specific DNA binding; DNA-binding transcription factor activity; RNA polymerase II cis-regulatory region sequence-specific DNA binding; chromatin binding; DNA binding; sequence-specific double-stranded DNA binding; transcription cis-regulatory region binding
Biological process: positive regulation of transcription by RNA polymerase II; transforming growth factor beta1 production; cell death; regulation of transcription by RNA polymerase II; positive regulation of DNA-templated transcription; regulation of DNA-templated transcription
Cellular component: nucleoplasm; RNA polymerase II transcription regulator complex; transcription factor AP-1 complex; chromatin; nucleus
Genetic constraint (gnomAD): Loss-of-function variants: 2 observed, 22.53 expected, observed/expected ratio (o/e) 0.0888, 90% interval 0.035 to 0.28. The upper end of that interval is the gene's LOEUF score, 0.28, which puts it in group 1 of 6, group 1 being the genes least tolerant of losing a copy. Missense variants: 333 observed, 447.2 expected, observed/expected ratio (o/e) 0.74, 90% interval 0.68 to 0.81. Synonymous variants: 179 observed, 192.34 expected, observed/expected ratio (o/e) 0.93, 90% interval 0.82 to 1.05.
Homologues: Orthologues: chimpanzee FOSL2 (100% identical), macaque FOSL2 (99% identical), dog FOSL2 (98% identical), pig FOSL2 (98% identical), guinea pig FOSL2 (98% identical), rabbit FOSL2 (98% identical), mouse Fosl2 (95% identical), rat Fosl2 (95% identical), tropical clawed frog fosl2 (75% identical), zebrafish fosl2 (67% identical), zebrafish fosl2l (22% identical), Drosophila melanogaster Atf3 (17% identical). Paralogues in human: FOS (48% identical), FOSL1 (44% identical), FOSB (41% identical), JDP2 (17% identical), ATF3 (16% identical), BATF (13% identical), BATF2 (13% identical), BATF3 (12% identical).
Diseases named in the same sentence as FOSL2 in open-access papers:
FOSL2 is named in the same sentence as 145 diseases in open-access papers, as found by Europe PMC text mining. Sharing a sentence is not in itself a finding about the gene and the disease. The quoted sentences say what the papers report.
breast carcinoma (28 papers, 2005 to 2025). "The results of this study revealed that the effects of ZN444B on breast cancer are in a FOSL2-dependent manner and warrant further investigation on the clinical association of FOSL2 during breast cancer development." (PMID 39010083, 2024). "The results of the present work lay a solid foundation for the clinical association of FOSL2 and breast cancer progression." (PMID 39010083, 2024). "Dual luciferase reporter assays and chromatin immunoprecipitation were performed to test the role of FOSL2 in regulating Wnt5a expression, and Wnt5a in the serum of the patients was measured to assess its clinical diagnostic value for breast cancer patients." (PMID 33754039, 2021). "Motif analysis predicts that a common mutation in breast cancer affects this region, and significantly disrupts the local binding affinity of several TFs, such as FOSL2." (PMID 32728046, 2020). "Studies have shown that over-expression of FOSL2 is associated with a higher invasive association with breast cancer and involved in breast cancer progression." (PMID 29330462, 2018). "And FOSL2 overexpression is associated with a more aggressive and invasive cancer phenotype (as found in breast cancer)." (PMID 24098529, 2013). "As explored in this study, FOSL2 is upregulated in breast cancer and a high FOSL2 level is associated with breast cancer development, and the protein level of FOSL2 was also remarkably downregulated under ZN444B treatment in breast cancer cells and primary tumors from 4T1 breast cancer model." (PMID 39010083, 2024). "Notably, CAF TCF12 has been linked to promoting breast cancer growth, whereas elevated FOSL2 levels in breast CAFs are significantly associated with angiogenesis and clinical progression in breast cancer." (PMID 38445456, 2024). "In breast cancer, FOSL2-expressing CAFs mediate VEGF-independent angiogenesis through the transcriptional activation of WNT5A, revealing novel anti-angiogenic therapeutic strategies targeting the tumor stroma." (PMID 41430036, 2025). "FOSL2 overexpression significantly abrogated the ZN444B-induced inhibition of breast cancer cell viability." (PMID 39010083, 2024). "We demonstrate for the first time that FOSL2 expression positively correlates with the progression and metastasis of breast cancer." (PMID 39010083, 2024). "FOSL2 expression was increased in breast cancer, and FOSL2 was more highly expressed in patients with advanced and metastatic malignancies." (PMID 39010083, 2024). "Compared to normal breast tissues, breast cancer tissues exhibited upregulated FOSL2 mRNA and protein levels." (PMID 39010083, 2024). "In our study, we found that FOSL2 expression positively correlates with breast cancer progression and metastasis." (PMID 39010083, 2024). "We then tested the effects of ZN444B on FOSL2 expression in an in vitro cell model and 4T1 breast cancer nude mice model." (PMID 39010083, 2024). "in vivo, ZN444B markedly downregulated FOSL2 protein expression in primary tumors in the 4T1 breast cancer model." (PMID 39010083, 2024). "Our findings demonstrated that ZN444B inhibits breast cancer cell growth and metastasis by specifically suppressing FOSL2 expression." (PMID 39010083, 2024). "Among the top 20 significantly downregulated proteins, FOSL2 was identified to be the most significantly downregulated protein in ZN444B-treated breast cancer cells." (PMID 39010083, 2024). "We found that ZN444B significantly inhibited FOSL2 expression, resulting in breast cancer growth and metastasis regression." (PMID 39010083, 2024). "Our findings support FOSL2 as a promising drug target for breast cancer and ZN444B as a potential candidate for the treatment of advanced breast cancer." (PMID 39010083, 2024). "Former studies have reported that FOSL2 plays a pivotal role in the progression of diverse human tumors and is amplified in a variety of human tumors, including breast cancer." (PMID 39010083, 2024).
breast carcinoma (continued). "The oncogenic activity of FOSL2 has been reported in breast cancer, ovarian cancer, colon cancer, and hepatocellular carcinoma." (PMID 37380804, 2023). "Using a loss-of-function approach, we confirmed the positive impact of FOSL2 on lincNORS expression in breast cancer cells, predominantly at a lower oxygen concentration." (PMID 32958772, 2020). "It has been recently shown that miR-597-5p targets FOSL2 in normal breast epithelial cells and downregulation of miR-597-5p during breast cancer prognosis promote migratory behavior in breast cancer cells." (PMID 31245295, 2019). "It has been earlier shown that miR-597-5p is downregulated in breast cancer patients and targets FOSL2 in normal breast epithelial cells." (PMID 31245295, 2019). "The regulation of FOSL2 in the context of breast cancer and ABCB1 in the context of ovarian cancer by miR-143-5p is yet to be studied." (PMID 31245295, 2019). "Moreover, transient FOSL2 knockdown by siRNA significantly decreased breast cancer cell growth and metastasis and increased the percentage of cell death." (PMID 39010083, 2024). "silencing FOSL2 expression decreased the sensitivity of breast cancer cells to ZN444B treatment." (PMID 39010083, 2024). "Overall, these results demonstrate that ZN444B significantly downregulated FOSL2 expression and may inhibit the proliferation and metastasis of breast cancer cells in a FOSL2-dependent manner." (PMID 39010083, 2024). "Our findings highlight the potential of FOSL2 as a new biomarker and therapeutic target for breast cancer and that targeting the HDAC1-Sp1-FOSL2 signaling axis with ZN444B may be a promising therapeutic strategy for breast cancer." (PMID 39010083, 2024). "Collectively, these results demonstrate that FOSL2 expression levels are positively correlated with breast tumor progression and that targeting FOSL2 may be a promising strategy for advanced breast cancer treatment." (PMID 39010083, 2024). "FOSL2 promotes cell proliferation, migration, and invasion in breast cancer and ovarian cancer." (PMID 38637555, 2024). "Next, FOSL2 levels were determined in clinical breast cancer specimens." (PMID 39010083, 2024). "Silencing FOSL2 expression decreases the sensitivity of breast cancer cells to ZN444B treatment." (PMID 39010083, 2024). "At present, the precise regulation of FOSL2 and the detailed mechanisms underlying its inhibition of breast cancer have not yet elucidated." (PMID 39010083, 2024). "Further mechanistic studies revealed that ZN444B inhibits Fos-related antigen-2 (FOSL2) expression in breast cancer cells by inducing the disassociation of HDAC1 and Sp1, inhibits the deacetylase activity of HDAC1 on Sp1 at K703, and abrogates the binding ability of Sp1 to the FOSL2 promoter." (PMID 39010083, 2024). "Furthermore, Kaplan-Meier survival curves indicated that high FOSL2 expression is closely related to the poor prognosis of breast cancer patients." (PMID 39010083, 2024). "FOSL2 expression is reported to be positively correlated with angiogenesis in breast cancer." (PMID 37380804, 2023). "FOSL1 and FOSL2 are reported to co-occupy selective gene targets in breast cancer cells." (PMID 35511484, 2022). "Interestingly, MDA-MB-231 and BT-549 breast cancer cells cocultured with CM from FOSL2-silenced CAFs had reduced proliferation and invasive ability in comparison with CM from control CAFs." (PMID 33754039, 2021). "The links between FOSL2-mediated breast development and breast tumor angiogenesis suggest that targeting FOSL2 in stromal fibroblasts may have significant value for breast cancer therapy." (PMID 33754039, 2021). "As we have known, miR-597 could act as a tumor suppressor in many cancer cells, and it could downregulate the FOSL2 to suppress breast cancer cell proliferation, migration, and invasion." (PMID 34458365, 2021). "In addition, enhanced FOSL2 expression has been documented in some carcinomas, such as colon 18, hepatocellular 19, ovarian 20 and breast cancer." (PMID 33754039, 2021).
breast carcinoma (continued). "Thus, this evidence supports the Wnt5a-dependent angiogenesis role of stromal FOSL2 in breast cancer." (PMID 33754039, 2021). "Moreover, we unveiled the clinical significance of the FOSL2/Wnt5a axis to gain insights into its pro-angiogenic function in the development and progression of breast carcinoma, suggesting potential novel therapeutic strategies for anti-angiogenic therapy." (PMID 33754039, 2021). "Herein, we found that FOSL2 was upregulated in activated CAFs of breast cancers." (PMID 33754039, 2021). "Together, our study supports the notion that stromal CAFs promote VEGF-independent pro-angiogenesis processes in breast cancer, and FOSL2-mediated Wnt5a expression and activation of downstream signaling are crucial for VEGF-independent angiogenesis of breast CAFs." (PMID 33754039, 2021). "Furthermore, FOSL2 expression positively correlates with breast cancer progression and metastasis." (PMID 39010083, 2024). "Therefore, the ability of ZN444B to block breast cancer growth and metastasis may be mainly achieved by suppressing the aberrant FOSL2 expression in breast cancer cells." (PMID 39010083, 2024). "To further confirm that ZN444B inhibits breast cancer in a FOSL2-dependent manner, we transfected cells with the pcDNA3.1-FOSL2 vector to rescue ZN444B-induced FOSL2 inhibition." (PMID 39010083, 2024). "A panel of breast cancer cells were treated with increasing ZN444B concentrations, and conventional RT-PCR revealed the suppression of FOSL2 mRNA." (PMID 39010083, 2024). "AP-1 motif was found enriched at ZEB1 binding sites and the AP-1 subunit FOSL2 was shown to co-occupy similar loci with ZEB1, suggesting a cooperation of ZEB1 with AP-1 in melanoma, in line with data in breast cancer cells." (PMID 38519642, 2024). "FOSL2 knockdown significantly weakened the inhibitory effect of ZN444B on breast cancer cell growth and metastasis in vitro, resulting in breast cancer cells being insensitive to ZN444B treatment." (PMID 39010083, 2024). "As shown in the heatmap of the 20 TFs from the mRNA microarray, FOSL2, SATB1 and GATA6 in CAFs were identified as candidate transcription factors in the progression of angiogenesis in breast cancer." (PMID 33754039, 2021). "This study also explored the detailed mechanism of the anti-breast cancer effects of ZN444B and provided the first evidence that FOSL2 may play a key role in breast tumors." (PMID 39010083, 2024). "Previous results have shown that FOSL2 overexpression leads to an increased invasive potential in breast cancer cells, but the mechanism has not been elucidated thus far." (PMID 25375657, 2014). "Conversely, FOSL-1 and FOSL-2, whose overexpression leads to enhanced tumour cell motility and invasion in breast cancer, colorectal cancer and mesothelioma, were not regulated by CBX7 (data not shown)." (PMID 24865347, 2014). "Our findings suggest that FOSL2 can be explored as a new biomarker for breast cancer and that targeting the HDAC1-Sp1-FOSL2 signaling axis with ZN444B may represent a novel option for the treatment of breast cancer." (PMID 39010083, 2024).
pulmonary fibrosis (28 papers, 2012 to 2026). Chronic progressive interstitial lung disorder characterized by the replacement of the lung tissue by connective tissue, leading to progressive dyspnea, respiratory failure, or right heart failure. "FOSL2 has also been implicated in pulmonary fibrosis, with its overexpression in macrophages promoting fibrotic changes in the lung." (PMID 38474264, 2024). "The systemic induction of c-Jun in mice leads to the development of multiorgan fibrosis with strong lung involvement, whereas ectopic expression of FOSL2 results in lung fibrosis, associated with vascular remodeling of the pulmonary artery." (PMID 36520540, 2023). "The expression of JUN (coding for c-JUN) was increased in many human fibrotic diseases, and strong expression of FOSL2 (encoding FRA-2) was observed in human samples of pulmonary fibrosis associated with vascular remodeling." (PMID 36520540, 2023). "Genes that had higher upregulation in the single-virus infections were predominantly increased late (days 4 and/or 6) and included genes associated with inflammation (Angptl4) or pulmonary fibrosis (Fosl2, Pappa, and Sphk1)." (PMID 34160242, 2021). "FOSL2, also known as FRA-2, is an activator protein 1 (AP-1) transcription factor and was reported to promote pulmonary fibrosis, cardiac fibrosis, and skin fibrosis, and be regulated by lncRNA UCA1 in ceRNA networks during tumorigenesis." (PMID 34715879, 2021). "Transgenic Fosl2 mice develop spontaneous lung fibrosis with Fosl2-expressing macrophages promoting lung fibrosis." (PMID 34972106, 2021). "Previous studies have demonstrated an increase in FOSL2 expression during lung fibrosis and in systemic sclerosis models, suggesting that upregulation of FOSL2 may be a common feature of many fibrotic disorders." (PMID 37662889, 2023). "Most of the significantly enriched TFs related to pulmonary fibrosis included STAT3, FOXP1, JUNB, ATF3, FosL2, BATF, Fra2 and AP‐1." (PMID 40464702, 2025). "Therefore, the differential effects on lung fibrosis between JUN and FOS from this study in fibroblasts and the FOSL2 expression in mice macrophages illustrates the complexity of AP-1 family functions in lung fibrosis." (PMID 34972106, 2021).
glioma (18 papers, 2012 to 2025). A benign or malignant brain and spinal cord tumor that arises from glial cells (astrocytes, oligodendrocytes, ependymal cells). "In gliomas, FOSL2 promotes tumors’ natural evolution and bone-marrow-derived macrophage polarization through the FOSL2-ANXA1-FPR1/3 axis in response to hypoxia signaling." (PMID 38286983, 2024). "To delve deeper into the connection between IGFBP7, FOSL2, the IGFBP7 Risk Score (IGRS), and glioma, we require extensive sample sizes and collaboration with multiple research centers." (PMID 39403379, 2024). "As for olfaction, a newly discovered risk factor for accelerating the progression of glioma, detected 17 target genes that exhibited consistent downregulation after naris occlusion; among them, ATF5 and FOSL2 were negatively correlated with GNAL." (PMID 38686055, 2024). "The transcription factor FOSL2 was most distributed in the C0 IGFBP7+ Glioma cells subgroup, and the distribution in other subgroups was different, with statistical differences." (PMID 39403379, 2024). "Secondly, we have only done scrna-seq and bulk RNA-seq analyses and in vitro experiments, and we need large sample and multi-center research to further explore the relationship between IGFBP7, FOSL2, the IGFBP7 Risk Score (IGRS), and glioma." (PMID 39403379, 2024). "FOSL2 has been identified to promote VEGF-independent angiogenesis in fibroblasts, and FOSL2 knock down in glioma endothelial cells increased blood tumor barrier permeability." (PMID 37856539, 2023). "We analyzed the TOP1 transcription factor FOSL2 of the C0 IGFBP7+ Glioma cells subgroup, which may be at the end of differentiation." (PMID 39403379, 2024). "Additionally, in vitro tests confirmed that transcription regulators like FOSL2 enhance glioma invasion and progression." (PMID 39403379, 2024). "Thus, FOSL2 has the ability to enhance the invasion and advancement of gliomas." (PMID 39403379, 2024). "By analyzing available public GBM datasets from the Cancer Genome Atlas (TCGA) and the Chinese Glioma Genome Atlas (CGGA), we revealed that FOSL2 was highly expressed in mesenchymal GBM, which was consistent with the expression characteristics of RUNX1." (PMID 38286983, 2024). "Next, we interrogated the glioma cohorts from TCGA and CGGA databases to further examine the expression and correlation characteristics of RUNX1, FOSL2, FN1, COL4A1, and LUM in GBM tumorigenesis." (PMID 38286983, 2024). "Expression profiling of the peritumoral brain around IDHmut gliomas also showed upregulation of SLC12A5, THBS1, VEGFA, FOSL2, and SYNPO, as has been previously reported in epileptic brain tissue." (PMID 37104042, 2023). "A subset of 7 transcription factors (STAT3, BHLHE40, CEBPA and B, RUNX1, FOSL2 and ZNF238) controlled most genes of the mesenchymal signature of gliomas; all but ZNF238 were significantly upregulated in the group 2 tumours compared to the other DIPG." (PMID 22389665, 2012). "The prognostic signature based on the expression profiles of RUNX1, FOSL2, and other ECM-related genes could be effectively utilized in predicting the prognosis and OS of glioma patients." (PMID 38286983, 2024). "Further studies should explore whether ATF5/FOSL2 and GNAL compete or inhibit each other upstream or downstream during the development of glioma." (PMID 38686055, 2024). "This suggests that among the TFs previously characterized (such as FOSL2, STAT3, BHLHB2, and RUNX1), FOSL1 and CEBPB might play a dominant role in the NF1-mediated MES transition that occurs in a glioma cell-intrinsic manner." (PMID 34399888, 2021).